CDKN2A (cyclin dependent kinase inhibitor 2A)
Diseases named in the same sentence as CDKN2A in open-access papers (continued):
Sharing a sentence is not in itself a finding about the gene and the disease.
cancer (continued). "For example, CDKN2A, E2F1, E2F2, and CDK4 were significantly overexpressed in 28, 26, 24, and 15 cancers, respectively." (PMID 35911954, 2022). "We found that 11.5% (3/26) of driver genes including PMS2, CDKN2A and TERT are significant in the prognosis at least two cancer types." (PMID 35962343, 2022). "There is a 5.1 kb CDR region within the CDKN2A gene, and most CDKN2A deletions lead to P16INK4A and P14ARF inactivation in human cancers." (PMID 36531022, 2022). "By the results above, we know that CDKN2A and CMTM8 were higher expressed in cancer tissues and the prognosis will be worse when they were up-regulated." (PMID 35429970, 2022). "LIAS and PDHB were cuproptosis promoters with low expression in cancer tissues, while GLS and CDKN2A were cuproptosis suppressors with high expression in cancer tissues." (PMID 35875097, 2022). "We found positive LASSO coefficients for the genes CDKN2A, EGLN3, KIF14, and RECQL4 that were upregulated in cancer compared with normal samples." (PMID 36552262, 2022). "Indeed, we also found in these cancers a significant co-occurrence of FGFR3 SVs with CDKN2A/B and TERT, as has been found previously, suggesting that it may be possible to stratify patients according to these alterations, but clinical data are required to confirm this hypothesis." (PMID 36462464, 2022). "Cyclin-dependent kinase inhibitors: The family of cyclin-dependent kinase inhibitor genes, CDKN2A (p16-INK4), CDKN2B (p15-INK4b), CDKN2C (p18-INK4c), and CDKN2D (p19-INK4d), are tumor suppressor genes generally inactivated in human cancers." (PMID 35056738, 2022). "The most common genes altered in potentially malignant diseases, cancer, and tobacco users include apoptosis-related genes BAX and BCL2 and cell-cycle-related genes such as cyclin-dependent kinases CDKN2A and CDK4." (PMID 35805720, 2022). "Then, we further characterized the 5.1 kb true CDR at the base resolution within the CDKN2A gene in cancer genomes using DNA sequencing data and confirmed the CDR using WGS datasets in all 18 GCs containing CDKN2A SCND." (PMID 36531022, 2022). "p16 (CDKN2A) is a member of the INK4 class of cell cycle inhibitors, which is often dysregulated in cancer." (PMID 35862385, 2022). "CDKN2A, also known as multiple tumour suppressor 1, is an inhibitor of CDK4 that suppresses cancer cell proliferation by arresting the cell cycle at phase G1." (PMID 35459137, 2022). "Next, we analyzed the correlation between MIR31HG expression and the deletion of these three genes (CDKN2A, CDKN2B, and MTAP) in 807 cancer cell lines from the CCLE database." (PMID 35570408, 2022). "While we were most interested in the cancerous squamous epithelial cells, the number of CECs (MUC5B, WFDC2) was larger than that of the cancer cells (TP63, KRT5, CDKN2A)." (PMID 35986392, 2022). "Given the strong association between CDKN2A and FAC, we indicated that regulating pathways involved in CDKN2A-associated genes or designing novel metal-based anticancer agents to induce ferroptosis and cuproptosis may guide us to develop new anti-cancer treatment strategies." (PMID 36052076, 2022). "In cancer, many promoters of potent tumour suppressor genes, such as CDKN2A, whose gene product p16INK4a is important for cell cycle control, and the DNA repair gene MGMT, are methylated and the genes are downregulated." (PMID 34638453, 2021).
cancer (continued). "When analyzing correlates of response at the gene level, CDKN2A, a tumor suppressor gene that inhibits CDK4/6 activity and is frequently deleted across cancers, was the strongest correlate of response to atezolizumab." (PMID 34172722, 2021). "Consistent with the present findings, BRG1 was found to suppress CDKN2A and IRF7 expression in GBM cancer stem cells." (PMID 33528916, 2021). "High expression has been detected in different cancers according to the ONCOMINE website, while the protein expression l of CDKN2A was verified, as shown in The Human Protein Atlas." (PMID 35004299, 2021). "The expression of both the CDKN2A and PLAU genes was upregulated in cancer tissues compared with that in normal tissues in both the Oncomine database and GEPIA database." (PMID 33968767, 2021). "Both genetic and epigenetic inactivation of function of CDKN2A gene (P16INK4a, P14ARF, or both) inhibited apoptosis and senescence of human cells and promoted experimental lung metastasis of cancer cells." (PMID 35004325, 2021). "Approximately 9.2% of cancers exhibited homozygous co-deletion of CDKN2A and MTAP, 3.7% of cancers had CDKN2A HD with wildtype or heterozygous MTAP, and 0.1% of cancers had MTAP HD with wildtype or heterozygous CDKN2A." (PMID 34556668, 2021). "Herein, we used NGS to interrogate the complex genomic landscape of 2457 patients with diverse cancers, of whom 507 patients harbored specific, potentially sensitizing G1/S phase cell-cycle (CDK4/6, CCND1/2/3, or CDKN2A/B) gene alterations." (PMID 33427211, 2021). "The downexpression of these miRNAs significantly reduced cancer cell proliferation and apoptosis by targeting FOXO-3, CLSPN, ACVR1B, E2F4 and PPP2CA and regulated cell cycle progression by targeting CDKN2A and FOXO-3." (PMID 34743742, 2021). "Studies showed that p21, p27, CDKN2A, MLH1, and RASSF1A were reactivated in two cancer cell lines after fenofibrate treatment." (PMID 33959155, 2021). "Overall, the six genes that had PVs with prevalences greater than one percent for any patient cohort (ATM, BRCA1, BRCA2, CHEK2, CDKN2A and FANCA) comprise a heterogenous group of genes that reflect the complexity of this cancer." (PMID 34255164, 2021). "The chromosome 9p21 (chr9p21) locus, which encodes the CDKN2A gene, is homozygously deleted in approximately 15% of all human cancers, with frequent codeletion of the MTAP gene, in 80–90% of tumors, along with CDKN2A deletion." (PMID 34006904, 2021). "Among the genes listed in the COSMIC50 database for cancer, seven blood lifespan cis-eGenes (ALDH2, BCL3, CDKN2A, FES, HIST1H3B, SH2B3, and SMARCA4) were identified (fold enrichment = 1.4, P = 0.22, hypergeometric test)." (PMID 32358504, 2020). "We report the significance of CDKN2A hydroxymethylation by HPV status, as well as many other cancer-related genes, such as CDH1, TIMP3 and SFRP4." (PMID 33203436, 2020).
cancer (continued). "Clustering analysis of the frequency of events targeting CDK4, CCND1, CDKN2A, and RB1 indicates analyzed human cancers fall into five distinct groups separated largely by RB1 status and the co-occurrence of CCND1, CDK4, and CDKN2A." (PMID 32242058, 2020). "Known cancer genes such as COL1A1 or STK11 were affected by duplications and other known genes such as CDKN2A, JAK2, PRDM1, FBXW7, or GOLGA5 were affected by deletions in several tumors of this subcluster." (PMID 32604718, 2020). "Thus, cytotoxic CD8+ T cells can directly reject Cdkn2a-deficient RT2-cancers, but senescence-induction through IFN-γ-mediated activation of the cell cycle regulators p16Ink4a/p19Arf was strictly needed to control those cancer cells that escape from cytotoxicity." (PMID 32165639, 2020). "This analysis suggested the hypermethylation of TWIST1, CDKN2A (ARF2), PIK3R5 and TBX2 are present in cancers of the breast, colon, lung and prostate." (PMID 33143142, 2020). "The BAMBI (Vanhara and Souček, 2013), LCN2, F13A1, CDKN2A, SLIT2, and CLU were reported to individually play a role in cancer development and progression." (PMID 33585439, 2020). "On the contrary, HPV− cancers exhibit more frequently amplifications of chromosome 7p and deletions of chromosome 9p that contain the EGFR and CDKN2A genes." (PMID 32403287, 2020). "On screening the top 200 linear model genes against cancer driver genes in the Cancer Gene Census, only four genes were found, namely BUB1B, CDKN2A, EZH2, and RECQL4." (PMID 31277598, 2019). "Two gain regions contained the well-known oncogenes EGFR (7p11.2) and CCND1 (11q13.3) and several known cancer suppressor genes, such as FHIT (3p14.2–p12.1), FAT1 (4q35.1), CDKN2A (9p21.3), and ATM (11q22.3–q24.3), reside within the 10 deletion regions." (PMID 31159251, 2019). "Other events not measured here may also affect dysregulation of some of these important cancer genes (e.g. epigenetic marks) and drive over- or under-expression such as that seen in a number of cases with relatively low levels of CDKN2A, but no identified inactivating mutation." (PMID 31341965, 2019). "We also compared the genes identified for LUAD and LUSC and found only five genes (ARID1A, CDKN2A, EGFR, MLL3, and RB1) are common for the two cancer types, demonstrating their different disease mechanism." (PMID 30828525, 2019). "Surprisingly, only eight identified genes (CCND1, CDK6, CDKN2A, KDM5A, MDM2, MLL3, PPP2R1A, and RB1) are shared by UniCovEx and CovEx, and they are all NCG cancer genes." (PMID 30828525, 2019). "The discriminating genes that most commonly shared among the 6 cancers were CDKN2A and PTCHD3, which were both selected in three cancers." (PMID 30704464, 2019). "For six of these, the deletion peaks map to well-known tumor suppressor genes (CDKN2A, PTEN, RB1, MAP2K4, NF1, and SMAD4) that are frequently deleted in multiple cancer types." (PMID 31341961, 2019). "Much like CDKN2A, the EZH2 gene displays a recurring regulation in seven cancer types (BRCA, KIRC, KIRP, LIHC, LUAD, PRAD, THCA)." (PMID 30005633, 2018).
cancer (continued). "Peaks involving important cancer genes such as CCND1, EGFR, ERBB2, FGFR1, AKT1, MYC, KRAS and CDKN2A/2B, which were confirmed in our data." (PMID 30131072, 2018). "Genomic analysis has been used to uncover intratumor heterogeneity in terms of copy number alterations in EGFR and CDKN2A/B/p14ARF as early events, and aberrations in PDGFRA and PTEN as later events during progression of cancer." (PMID 30374421, 2018). "Histone Deacetylase Inhibitors (HDIs) have been shown to activate silenced genes including CDKN1A, CDKN2A,SALL3, RARb2, TERT and GATA4, in the human cancer cells by active DNA demethylation of their respective promoters." (PMID 28077797, 2017). "These include cancer hallmarks of various types: oncogenes (BCL2, BRAF), caspases (CASP6/7), transcription factors (E2F3), cell cycle genes (CDC42, CDK2, CDKN2A), cancer related kinases (JAK2/3, MAPK4/6/14) and DNA repair genes (BRCA1, PARP1 and RAD50)." (PMID 28059167, 2017). "In cluster 2, the key genes CDKN2A, HSP90AB1, TRAF2 and RAF1 are effective agents in cancer pathway." (PMID 29379595, 2017). "p16INK4A/CDKN2A and p15INK4B/CDKN2B, which are CDKIs for CDK4/6, are downregulated in several types of cancer." (PMID 28931650, 2017). "CDKN2A/B protein products restrict cell-cycle progression by inhibiting CDK4/6 kinase activity, and aberrations in these genes lead to cancer progression by dysregulation of the cell cycle." (PMID 29089060, 2017). "We recorded overexpression of cancer related genes including ALK, CDKN2A, and EZH2 compared with normal skin." (PMID 28359267, 2017). "For this reason, it seems unlikely that the induction of CDKN2A and CDKN2B expression observed in both these cancers is related to a reduction in expression of the BMI1 component of PRC1." (PMID 29069809, 2017). "We examined DNA methylation levels of SFRP1, SFRP2, SFRP5, DKK2, DKK3, mir34b/c, RASSF1A, IGFBP7, CDKN2A, and MLH1 in cancerous glands and normal crypts isolated from cancer tissue and the surrounding normal mucosa." (PMID 28533824, 2017). "HDIs, TSA, depsipeptide and sodium butyrate, were shown to enhance the expression of genes such as CDKN2A, CDKN1A, SALL3, RARb2, TERT and GATA4 in human cancer cell lines by active DNA demethylation of their respective promoters." (PMID 28077797, 2017). "Overwhelmingly, these papers studied the differentially methylated region (cancer DMR, cDMR) on the 3′ end of the CpG island that overlapped the first exon of CDKN2A." (PMID 27170255, 2016). "CDKN2A and CDKN2B are inactivated in a number of different cancers, and mono- or biallelic deletion of CDKN2A are recurrent events in childhood ALL7." (PMID 26463672, 2015). "Among them, the following well-known cancer genes were found: MET, CDK4, MDM4, EGFR and PIK3CA (amplifications), and CDKN2A, MLLT3, HRAS, CARS and NF1 (deletions)." (PMID 23408991, 2013). "The products of CDKN2A can therefore be key mediators of OSR and potent barriers to the “immortalization” of cells in culture and the development of cancers in vivo." (PMID 24167519, 2013). "In the spleen, 8/84 cancer-related genes were affected in FLT mice compared to AEM controls (P<0.05; up: Cdkn2a; down: Birc5, Casp8, Ctnnb1, Map2k1, Mdm2, NFkB1, Pdgfa)." (PMID 24069384, 2013). "Moreover, PC families with BRCA1/2 and CDKN2A mutations were not excluded from the study; these families may have greater familiarity with cancer screening tests and their attitudes may differ in important ways from other PC family members." (PMID 22738386, 2012).
cancer (continued). "Since methylation of CDKN2A occurs more frequently in MSI-H and shows the typical features characteristic of unstable cancers, we evaluated the relationship between CDKN2A methylation and prognostic factors in both MSS/MSI-L and MSI-H cases." (PMID 22925370, 2012). "TBX2 and its close relative, TBX3, negatively regulate cell cycle control genes and CDKNs, specifically CDKN2A, CDKN2B, and CDKN1A and are often upregulated in several cancers." (PMID 22829758, 2012). "Accumulating evidence has shown that hypermethylation in the promoter region of CDKN2A or overexpression of CCND1, which results in RB1 dysfunction, frequently occurs in various types of cancers." (PMID 21447152, 2011). "The INK4a/ARF/INK4b locus (also known as CDKN2A and CDKN2B) plays a pivotal role in aging and cancer." (PMID 21347436, 2011). "Several frequently methylated loci identified in early studies, for example CDKN2A/p16, CDH13, MGMT and RASSF1 remain viable markers when assessed in a larger context, providing support for their role in cancer development/progression." (PMID 18947422, 2008). "Recently a report examining the methylation of CDH13, CDKN2A/p16, FHIT, RARB, RASSF1A and ZMYND10 (BLU) in which methylation of any 2 loci in plasma was considered cancer positive showed 73% sensitivity and 82% specificity." (PMID 18947422, 2008). "Known cancer genes included focal amplifications of MYC (8q24.21), KRAS (12p12.1) and AKT2 (19q13.2), and homozygous deletions of TGFBR2 (3p24.1) and CDKN2A (9p21.3)." (PMID 18535672, 2008). "We suggest that BIN1 promoter CGI, similarly to those of CDKN2A or RASSF1A genes, is composed of the two functionally unequal parts, 3' being frequently and densely methylated and 5' being lowly methylated in cancer." (PMID 17477881, 2007). "The methylation level of the LOH-H cancers was significantly lower at the 5'-transitional CpG sites of the VDR, FLJ43855, CDKN2A, MUC8, MAGEA2, and MSLN genes." (PMID 16827945, 2006). "The LOH-L cancers had a significantly higher methylation level at the 5'-transitional CpG sites of the MLH1 and CDKN2A genes." (PMID 16827945, 2006). "Secondly hypermethylation of CDH1, CDKN2A, and SFRP1, was rare in PCa tissues (<5% of the specimens), although they were hypermethylated in cancer cell line controls." (PMID 15292941, 2004). "Patients and Methods: We examined 72 Mexican patients (14 probands from distinct families, 48 relatives, and 10 nonrelated probands) carrying the CDKN2A (c.146T>C) form three hereditary cancer centers between September 2023 and September 2025." (PMID 42194989, 2026). "An overwhelming body of evidence suggests that MTAP and the cancer suppressor gene cyclin-dependent kinase inhibitor 2A (CDKN2A) are closely situated and concurrently absent in a subset of cancers." (PMID 40430461, 2025). "Consistently, loss of 9p21.3/CDKN2A,CDKN1A were observed in virus-negative cancers (OR = 4.96, 95% CI = 3.65–6.73, q = 1.77e-25)." (PMID 40595559, 2025).